UMOD (uromodulin)
Diseases named in the same sentence as UMOD in open-access papers (continued):
Sharing a sentence is not in itself a finding about the gene and the disease.
cancer (10 papers, 2010 to 2026). A tumor composed of atypical neoplastic, often pleomorphic cells that invade other tissues. "Additionally, we identified nearly 200 human proteins, including promising population-level health indicators, such as immunoglobulins, uromodulin, and cancer-associated proteins." (PMID 41561306, 2026). "In addition, UMOD and MCP-1 were associated with cardiovascular and cancer-related deaths, respectively." (PMID 37533144, 2023). "Immunoglobulins and highly abundant urinary proteins (serum albumin, uromodulin, serotransferrin) were excluded due to their high abundance in biological samples and the lack of specificity for cancer, resulting in 170 proteins." (PMID 35454907, 2022).
infection (6 papers, 2015 to 2025). The state of being infected such as from the introduction of a foreign agent such as serum, vaccine, antigenic substance or organism. "Noting that UMOD‐deficiency has been reported to render mice more susceptible to bladder colonization with Escherichia coli, it was important to ensure that none of the experimental mice had evidence of infection." (PMID 29595914, 2018). "Because structurally related human proteins Uromodulin and GP2 bind to bacteria and control infection, we hypothesized that omcin genes have a similar function." (PMID 39309883, 2024).
tumor (6 papers, 2013 to 2025). "For example, MAPK10 isoforms showed distinct phenotypic correlations, while COL1A1 and UMOD displayed gene-level coordination in regulating tumor stemness." (PMID 41048343, 2025). "Only two proteins that were more abundant in the urine of tumor patients in comparison to healthy volunteers decreased: uromodulin and OPN." (PMID 30813269, 2019). "It is possible that uromodulin is related to an inflammatory state that is observed in tumor patients, since its involvement in inflammatory processes in kidney injury has been demonstrated." (PMID 30813269, 2019).
kidney (5 papers, 2017 to 2025). "However, in vitro studies have shown decreased expression of UMOD following kidney ischemia-reperfusion injury." (PMID 28613246, 2017). "Furthermore, UMOD deficient mice showed delayed and incomplete recovery from acute kidney injury after IRI, which is explained by a lack of upregulation of uromodulin expression after IRI." (PMID 34208140, 2021).
bacterial infection (4 papers, 2014 to 2024). "Uromodulin-knockout mice have a great susceptibility to bacterial infection and this gene is thought to regulate inflammatory signals to allow healing." (PMID 24670243, 2014). "It was also found that Tamm–Horsfall protein (THP or uromodulin, UMOD) acted as a crucial defense molecule against viral and bacterial infections in the urinary tract by its binding activity." (PMID 29361765, 2018). "Based on these characteristics of omcin genes, we hypothesized that their functions are similar to that of uromodulin and GP2, whose encoded proteins bind to and control bacterial infections in urinary and intestinal tract." (PMID 39309883, 2024). "While zgc153932 does not have a matching homolog in the mammalian genomes, it showed sequence similarity to uromodulin and Glycoprotein2 (GP2), which are epithelial proteins controlling bacterial infection." (PMID 39309883, 2024).
genetic disorder (3 papers, 2014 to 2024). "UAKD is a progressive hereditary disease and belongs to the endoplasmic reticulum (ER) storage diseases due to maturation defect of mutant UMOD and its retention in the enlarged ER of TALH cells." (PMID 25409434, 2014).
cardiac diseases (2 papers, 2024). "Given the interconnected nature of cardiac diseases and their profound impact on overall health, investigating the relationship between uromodulin and these conditions holds promise for advancing our understanding of cardiovascular pathophysiology." (PMID 39049957, 2024).
UMOD also shares sentences with these, for which no sentence is quoted: essential hypertension (4 papers); melanoma (3); Renal cyst (3); injury (2); polycystic liver disease (2); renal dysfunction (2); renal tubular disease (2); toxic (2); acute tubular necrosis (1); Alport syndrome (1); ANCA‐associated vasculitis (1); aortic regurgitation (1); atherosclerosis (1); atrial fibrillation (1); autosomal dominant disease (1); Blindness (1); Blood Pressure (1); cardiomyopathy (1); chronic kidney failure (1); Chronic tubulointerstitial nephritis (1); ciliopathies (1); Cirrhosis (1); congenital anomalies of the kidney and urinary tract (1); coronary atherosclerosis (1); cystitis (1); Fanconi syndrome (1); fibrosis (1); fructose intolerance (1); Gitelman syndrome (1); glomerulopathies (1).
A further 31 diseases each share a sentence with UMOD in 1 paper.